STAT3 (signal transducer and activator of transcription 3)
Diseases named in the same sentence as STAT3 in open-access papers (continued):
Sharing a sentence is not in itself a finding about the gene and the disease.
tumor (continued). "The active form of STAT3, pSTAT3, enhances tumor growth and tumor survival, cell migration, cell invasion, angiogenesis and downregulates the immune response." (PMID 33121489, 2020). "HCK inhibition decreases tumor growth, perhaps by impairing TGFBeta-SMAD signaling pathways or STAT3-dependent tumor growth." (PMID 33233470, 2020). "Long-term STAT3 activation blocks anti-tumour immune response, which supports the growth of cancer cells." (PMID 32863742, 2020). "STAT3 is an important member of the STATs family and can regulate a variety of key tumor factors, including the anti-apoptotic gene BCL-2 and the cell cycle control gene c-MYC." (PMID 33746736, 2020). "Among these, a natural product available in the NCI DTP repositoryhas the ability to inhibit activation and phosphorylation of STAT-3 selectively,which leads to apoptosis of tumor cells (Zhanget al., 2007)." (PMID 32167126, 2020). "UTMC-mediated delivery of STAT3 decoy or mutant decoy was performed in a separate group of CAL33 tumor-bearing mice, and tumors were harvested 48 h later and analyzed for target gene expression." (PMID 33206698, 2020). "The genes induced by both NF-κB and STAT3 are critical regulators of cellular proliferation, angiogenesis, genomic instability, resistance to apoptosis, invasion and metastasis of tumor cells." (PMID 33182552, 2020). "Because STAT3 is highly expressed in cancer tissues, the level of its activated form (p-STAT3 protein) in tumour tissue is also higher than that in other tissues." (PMID 32382281, 2020). "The mice used in this survival study were sacrificed on day 42, and tumor tissue was collected to detect PD-L1 and p-STAT3 by IHC." (PMID 32483429, 2020). "IL-6 is considered as a malevolent player that promotes tumor initiation and macrophages infiltration and is found to be closely related to STAT3 (Signal Transducers and Activators of Transcription-3)." (PMID 32102330, 2020). "In combination with paclitaxel, momelotinib inhibited tumor growth, suppressed STAT3 activation, reduced expression of the stem cell marker OCT4, significantly increased the time to recurrence, and decreased tumor burden." (PMID 33521321, 2020). "For further validation of our quantitative analysis method (determination of the tumor invasion index and the space occupying growth index), tissue slice co-cultures with spheroids from MZ-54 wildtype vs. MZ-54 STAT3 knockout (KO) cells were compared." (PMID 32967361, 2020). "IL-6 produced by primary tumor stroma induced STAT3 signaling in 80–90% hepatocytes, compared to activation in 2% hepatocytes in non-tumor bearing mice." (PMID 32230953, 2020). "Additional work is needed to understand the impact of discrete microenvironments (e.g., tumor, TdLNs) on STAT3 signaling in CD103+ cDC1s as well as CD103+ cDC1-mediated T cell activation and recruitment." (PMID 31947933, 2020). "TAMs can promote CRC migration, invasion, and circulating tumor cell (CTC)-mediated metastasis via the JAK2/STAT3/miR-506-3p/FoxQ1 axis, enhancing macrophage recruitment through the production of CCL2 by tumor cells." (PMID 32943996, 2020). "Recently, we found that the chr8p tumor suppressor SH2D4A interacts with STAT3 outside the nucleus thereby inhibiting tumor-promoting STAT3 signaling." (PMID 33257655, 2020). "Taken together, these data indicate that atorvastatin can induce atypical cellular senescence in HCC cells to inhibit tumor growth, an effect mediated by downregulation of hTERT through suppression of the IL-6/STAT3 pathway." (PMID 32257389, 2020). "Among all immunosuppressive signals related to HCC tumor immunity, the NF-κB/IL-6/STAT3 inflammatory axis is crucial for promoting tumor proliferation and evasion, with protumor cytokines being highly upregulated by this pathway." (PMID 32595757, 2020). "Our findings confirm other studies that showed inhibition of JAK and STAT3 protein activation results in growth inhibition and apoptosis in tumor cells both in vitro and in vivo." (PMID 33536913, 2020).
tumor (continued). "In our previous studies, we found that IL-37 is a potential novel tumor suppressor by inhibiting IL-6 expression to suppress STAT3 activation and decreasing epithelial-to-mesenchymal transition." (PMID 33489865, 2020). "Evidence suggests that IL-6, a cytokine known for its pro-tumor behavior via JAK2/STAT3 signaling, can attract neutrophils within an immunosuppressed microenvironment." (PMID 31991796, 2020). "The release of ROS is controlled by NADPH oxidase (NOX) activity, whose expression is regulated by STAT3, resulting in tumor progression through immune evasion, proliferation, angiogenesis, and metastasis." (PMID 33291616, 2020). "LIF also enhances tumor progression by promoting cell cycle progression and invasive activity of tumor cells via STAT3 activation, as is the case of other IL-6 family of cytokines." (PMID 32023940, 2020). "In prostate cancer, B cell-secreted lymphotoxin (LT) was shown to drive STAT3 signaling to promote tumor growth." (PMID 33193299, 2020). "Encouragingly, circulating exosome miR‐148a was found in serum and promoted tumour progression by targeting CADM1 to activate STAT3 pathway, suggesting its clinical value." (PMID 32412186, 2020). "STAT3 signaling is required not only by the epithelial cells in the tumor microenvironment but also by cancer stem cells." (PMID 32670290, 2020). "Through the STAT3 pathway, exogenous IL-6 induces the secretion of tumour-derived IL-6 to create a microenvironment that is favourable for the metastasis of CRC cells." (PMID 32760201, 2020). "The continuous activation of STAT3 in tumor cells increases the expression of cytokines (transforming growth factor β [TGF-β] and IL-10) and then promotes tumor development and metastasis in a positive-feedback manner." (PMID 32487755, 2020). "In particular, cytokine-activated STAT3 can promote cancer proliferation and invasion while suppressing anti-tumor immunity by regulating the expression of immune checkpoint proteins PD-1, PD-L1 and CTLA4." (PMID 33216733, 2020). "Briefly, HOXA11-AS regulates STAT3 expression by acting as a miRNA sponge in liver cancer, thereby accelerating tumor growth and metastasis." (PMID 32928281, 2020). "SH2 domain containing protein 5, or SH2D5, is a transcriptional target of YAP/TAZ and promotes tumor growth through interaction with transketolase, a regulator of the STAT3 signaling pathway." (PMID 33614496, 2020). "Hsa-miR-122 and Has-miR-146a-5p are both thought to be involved in regulating STAT3 signaling, a key pathway involved in immune suppression in tumor microenvironment." (PMID 32228601, 2020). "This latter study also reported that STAT3 mRNA levels were higher in ex vivo cultured BC tumors derived from post-chemotherapy TNBC biopsies compared with pre-chemotherapy tumor tissues." (PMID 33585241, 2020). "Recent evidence indicates that the combination of STING agonists with STAT3 inhibitors can enhance tumor immunogenicity and optimize the immunotherapeutic effects." (PMID 32972405, 2020). "There are several compounds that are known to exert anti-tumor effects through their indirect or direct action on STAT3 and/or STAT5 signaling." (PMID 31963765, 2020). "In a mouse melanoma and lung cancer model, B cells with activated STAT3 contributed to increased tumor growth through the promotion of angiogenesis." (PMID 33193299, 2020). "On the same hand, unlike conditioned medium from human adipose MSCs, eicosapentanoic acid-treated adipose MSCs reduced mRNA levels of the tumor-associated genes FASN, STAT3, cIAP-2 in MDA-MB-231 and MCF-7 breast cancer cell lines." (PMID 33330442, 2020). "IL-6 has pleiotropic effects on various cell types in the tumor microenvironment, which leads to the regulation of pro-oncogenic transcription factors NF-κB and STAT3." (PMID 32138303, 2020). "In line, STAT3 is constitutively activated in tumor-infiltrating immune cells including DCs, and ablating STAT3 triggers the immune cells to inhibit tumor growth and metastasis." (PMID 33193420, 2020).
tumor (continued). "This relationship is of importance in the tumor microenvironment, since present cells are able to secrete interleukins that in turn activate the STAT3 signaling pathway, leading to the elevated progression and malignancy of GC cells." (PMID 32545648, 2020). "Meanwhile, STAT3β, a STAT3 splicing isoform, is related to the inhibition of tumor growth and chemosensitivity." (PMID 32872659, 2020). "STAT3 activation is tightly controlled in healthy cells, and is constitutively activated during tumorigenesis, where in it upregulates genes involved in tumor cell proliferation, invasion, migration, and angiogenesis." (PMID 33343368, 2020). "In previous studies, the STAT3 inhibitor CPA-7 induced tumor cell death in GL26 mouse GBM and HF2303 human GBM stem cells." (PMID 33173024, 2020). "Downregulation of miR-204 also contributes to malignant progression via the MAPK pathway modulation, by activating STAT3, which acts as a transcription factor when translocated into the nucleus, promoting tumor development." (PMID 32674318, 2020). "Phosphorylated STAT3 was also readily detected in MPM cell lines newly derived from surgical MPM tumor specimens." (PMID 33374980, 2020). "HMGA1 regulates the expression of various tumor progression driver genes, such as STAT3, a signal transducer and activator of transcription for which expression is associated to a refractory status in diverse tumors." (PMID 32503270, 2020). "Further studies found that S1PR1 signaling in T cells enhanced tumor invasion by Treg in a STAT3‐dependent manner, reduced CD8+TIL in TME, and increased breast cancer and melanoma growth in mouse models." (PMID 32875727, 2020). "Other studies have demonstrated that STAT1 activation is upregulated in M1 macrophages and is correlated with developing antitumor responses, while STAT3 is considered an oncogene promoting tumor growth." (PMID 33036138, 2020). "Further, the results suggested that IL-6 derives from tumor-infiltrating macrophages that can induce CD47 expression in HCC by activation of the STAT3 signaling pathway." (PMID 32466488, 2020). "Other molecules have been reported in cancer that can influence tumor growth through regulation of the IL-6/STAT3 signaling pathway." (PMID 32283655, 2020). "Although Stat3 phosphorylation is strictly regulated in physiological conditions, over-activation of Stat3 has been detected in a variety of human cancers, suggesting a key role for this transcription factor in tumour initiation and progression." (PMID 32467235, 2020). "The CTLA4apt-STAT3 siRNA effectively boosts antitumor immune responses and slows tumor growth by lowering STAT3 activation in mouse models." (PMID 33050544, 2020). "We previously demonstrated that UTMC treatment with STAT3 decoy-loaded cationic lipid microbubbles inhibited tumor growth in mice harboring murine skin squamous cell (SCC-VII) tumors." (PMID 33206698, 2020). "According to an in vivo study of Jun Liao etal, the tumor suppression effect of NC was also attributed to the JAK1/STAT3 cascade signaling inhibition." (PMID 32931665, 2020). "This is due to the boosted STING that negatively regulates a STAT3 propagated crosstalk between immune cells and tumor cells." (PMID 33288772, 2020). "Taken together, the present observations indicated that PRP3 served as a tumor active factor in cSCCs by targeting the JAK2/STAT3 pathway." (PMID 32483193, 2020). "It was found that up-regulated p-STAT3 expression in HCC tissues was associated with HBV infection, larger tumor diameter, intrahepatic metastases, PVTT and tumor differentiation." (PMID 31942180, 2020). "The expression of STAT3 and its relationship with tumor stage were explored by Tumor Immune Estimation Resource (TIMER), Human Protein Altas (HPA), and UALCAN databases." (PMID 32486001, 2020).
tumor (continued). "This review outlines the role of the STAT3 pathway in tumor immunity, summarizes the recent progress in STAT3-centered anti-cancer approaches, and highlights future directions for the clinical immunotherapy." (PMID 32972405, 2020). "STAT3 signaling in tumor and stromal cells upregulated the expression of pro-survival and pro-angiogenic genes, and hence drove tumor growth." (PMID 32121394, 2020). "We recently found tumor growth inhibition of 201T- and H1975-derived xenografts after the daily intravenous administration of STAT3 decoy (5 mg/kg/day), 5 days per week for 14–20 days." (PMID 33206698, 2020). "Collectively, these observations support a prominent role for CD44 and STAT3 crosstalk in mediating tumor and TAM interactions within the ovarian TME." (PMID 33335857, 2020). "Studies have shown that G6PDH promotes tumor cell proliferation mainly via ROS-stimulated p-STAT3 signaling activation and upregulation of cyclin D1 expression in RCC cells." (PMID 33123534, 2020). "Inflammatory mediators such as Hmgbl, IL-23 and IL-17 can promote tumor growth by activating the IL-6/STAT3 pathway in a mouse model of melanoma." (PMID 32283655, 2020). "It would also be of interest to investigate the possible impact of miR-124 modulation in other tumor driver pathways in addition to STAT3." (PMID 33333886, 2020). "NETs itself directly upregulates the Toll-like receptor 9 (TLR9) pathways in DLBCL and then NF-κB, STAT3 and p38 pathways promoting tumor progression." (PMID 32731512, 2020). "Our data provide evidence for elucidating the leading role of STING in regulating STAT3-propagated crosstalk between immune cells and tumor cells." (PMID 33288772, 2020). "The mechanisms leading to STAT3 activation are not fully understood; however, we recently found that miR-124, a known STAT3 regulator, is robustly silenced in MF tumor-stage and CTCL cells." (PMID 33333886, 2020). "We found that levels of STAT3 phosphorylation decreased in the livers of LTsc1KO mice as compared with TSC1fl/fl mice, and in tumors as compared with non-tumor areas of the liver in LTsc1KO mice." (PMID 32363190, 2020). "Subsequently, the expression of G6PD, p-STAT3, and p65 in tumor xenografts was compared by Western blot analysis." (PMID 33041664, 2020). "Activated STAT3 was found in diverse cancers, such as GC, promoting tumor cell growth, proliferation, anti-apoptosis, cancer angiogenesis and metastasis." (PMID 32576206, 2020). "In this study, we evaluated the role of STAT3 and IL-6 in a tumor microenvironment mediated drug resistance in human MBs." (PMID 33279931, 2020). "Phosphorylated STAT3 increases tumor cell proliferation, migration, and invasion by increasing the expression of genes such as b-cell lymphoma 2 (Bcl2), cyclin D1, and c-myc." (PMID 32432040, 2020). "Rescue experiments indicated that restoration of STAT3 expression attenuated the tumor-suppressive actions of miR-769-5p in RB cells." (PMID 32369777, 2020). "Since we observed BCL2L10 transactivation by STAT3 in the model cell line HEK293, it is very likely that STAT3 drives BCL2L10 upregulation in other tumor types presenting constitutive activity of STAT3." (PMID 33396645, 2020). "Lastly, STAT3 is one of the main transcription factors that govern MDSC functions to promote tumor proliferation and suppress immune-mediated cytotoxic cell death of cancers." (PMID 33291616, 2020). "Metformin down-regulated the function of G-MDSCs through AMPK/STAT3 pathways, delaying tumor progression in CT-26 cell colon cancer mouse model." (PMID 33613512, 2020). "Our recent study found that YM155 decreased the activity of STAT3 and increased the radiosensitivity of glioblastoma, one of the most radioresistant tumor types." (PMID 32733808, 2020). "We also found an interaction between SLC2A1‐AS1 and STAT3, the latter of which is a transcription factor that plays crucial roles in tumour glycolysis." (PMID 32174012, 2020).
tumor (continued). "Our findings consolidate the therapeutic importance of STAT3 in GBM as a fundamental regulator of key tumour features." (PMID 32486489, 2020). "In summary, these findings indicate that HOTAIR promotes xenografted PCa tumor growth by activating STAT3 signaling and increasing PCSLCs population." (PMID 32657763, 2020). "As a next step towards clinical translation, we sought to determine the anti-tumor efficacy of our STAT3 decoy delivery platform against human HNSCC and the effect of higher STAT3 decoy microbubble loading on tumor cell inhibition." (PMID 33206698, 2020). "STAT3, an oncogene, contributes to insensitivity of chemotherapy and radiotherapy in tumor, reduces the clinical efficacy." (PMID 32872659, 2020). "STAT3 also plays a pivotal role in a plethora of tumor-infiltrating immune cells that predominantly comprise the TME and recent comprehensive reviews have covered this topic." (PMID 32972405, 2020). "Treg cells from 12B1 tumor-bearing animals suppressed the function of DCs in a TGF-β- and IL-10-dependent manner and were associated with the activation of STAT3." (PMID 32872659, 2020). "An extensive body of literature has established a role for STAT3 in the induction of pro-inflammatory cytokines, tumor progression, initiation, metastasis, chemoresistance, and immune evasion." (PMID 32023849, 2020). "In breast cancer settings the substitution of Ser727 for alanine or aspartate in mitoSTAT3 affects tumor development in an independent manner of STAT3 nuclear activity." (PMID 33584695, 2020). "Our results showed that the accumulation of CD8+ T cells in advanced-stage tumor was systematically inhibited by Th17 cells via IL-17A/STAT3/CXCR3 axis." (PMID 32503584, 2020). "In carcinogenesis, STAT3 upregulates genes that can promote tumor survival, angiogenesis, resistance to cell death, and cell cycle progression." (PMID 31963897, 2020). "QRHX also reduces the expression of CXCL12/CXCR4 and the phosphorylation of JAK2/STAT3 in tumor tissues." (PMID 33224886, 2020). "Early pre-clinical studies utilised AZD1480, a JAK1/2 inhibitor, and demonstrated STAT3 inhibition and anti-tumour activity in HPV- HNSCC PDX models." (PMID 32899142, 2020). "In particular, in line with increased circulating IL6 in the mHCT116 tumor hosts, we also reported increased phosphorylated STAT3 levels in the skeletal muscle of mHCT116-bearing animals." (PMID 31915140, 2020). "The activation of Stat3 in normal cells is fast and transient, but it is continuously activated in tumor cells." (PMID 32258099, 2020). "STAT3 enhancement of tumor motility and EMT-like characteristics in GBM cells correlated with Slug expression." (PMID 32872659, 2020). "The critical involvement of STAT3 in survival and proliferation of tumor cells has been previously reported." (PMID 32326395, 2020). "In contrast to pSTAT3 activation, this analysis demonstrated the inability of any treatment in tumor‐bearing mice to significantly limit the importance of STAT3 target gene regulation relative to cachectic controls." (PMID 31930715, 2020). "The research of STAT3 inhibitors has led to several potent anti-tumor candidates over the years (e.g., Stattic, S3I-201, and erasin)." (PMID 32752073, 2020). "Our in vivo data demonstrate where primary tumor phospho-STAT3 is reduced, there is a reduction in metastatic lung colonisation." (PMID 32472077, 2020). "In that study, the tumorigenic activities of PKR were attributed to both overexpression of phosphorylated and total PKR in primary tumor tissues relative to the surrounding normal tissues and to STAT3 transcription factor." (PMID 32198380, 2020).